TRAF3 (TNF receptor associated factor 3)
Diseases named in the same sentence as TRAF3 in open-access papers (continued):
Sharing a sentence is not in itself a finding about the gene and the disease.
histiocytic sarcoma (3 papers, 2018 to 2023). An aggressive malignant neoplasm with a poor response to therapy, usually presenting as stage III/IV disease. "Myeloid-specific Traf3 KO causes histiocytic sarcomas of macrophage origin." (PMID 33185187, 2020). "However, because histiocytic sarcoma in humans is a rare malignancy with sparse pathologic and cytogenetic data, potential TRAF3 genetic alterations in human histiocytic sarcomas require future investigation." (PMID 30294322, 2018). "Interestingly, specific deletion of TRAF3 from myeloid cells (granulocytes, monocytes, and macrophages) leads to spontaneous development of histiocytic sarcomas derived from TRAF3−/− tissue-resident macrophages in aging mice." (PMID 30294322, 2018). "Two other mouse models with functional relevance to TRAF3, Dok1−/−Dok2−/−Dok3−/− mice and humanized TLR7/TLR8 transgenic mice, also spontaneously develop histiocytic sarcomas." (PMID 30294322, 2018). "In addition to the phenotype of histiocytic sarcoma, aging myeloid cell-specific TRAF3−/− (M-TRAF3−/−) mice spontaneously develop chronic inflammation and other cancers that often affect multiple organs including the gastrointestinal tract." (PMID 30294322, 2018).
melanoma (3 papers, 2013 to 2024). A malignant, usually aggressive tumor composed of atypical, neoplastic melanocytes. "Furthermore, TRAF3 demonstrated carcinogenic properties in ACC (OS: n = 79, p < 0.001), LIHC (OS: n = 368, p = 0.010), THYM (OS: n = 118, p = 0.021), and Uveal Melanoma (UVM) (OS: n = 80, p < 0.001)." (PMID 38825674, 2024).
Splenomegaly (3 papers, 2018 to 2021). Abnormal increased size of the spleen. "An NFKB1 variant was found in a patient with recurrent autoimmune hemolytic anemia, antibody deficiency and splenomegaly and a TRAF3 variant was found in a patient with antibody deficiency." (PMID 34992599, 2021). "When TRAF3 is deleted specifically in B cells via CD19Cre (B-TRAF3-KO), mice develop autoimmune manifestations including splenomegaly, lymphocyte infiltration in liver and immune-complex deposition in kidney at the age of 9-12 months." (PMID 33841447, 2021). "However, when TRAF3/BCL2 double-tg mice became older they began developing severe lymphoid dyscrasias, characterized by massive splenomegaly, and overt disseminated lymphadenopathy." (PMID 30687320, 2018). "In this report, we show that the combination of TRAF3 and BCL2 overexpression in B cells leads over time to severe lymphadenopathy, splenomegaly and extranodal lymphoid infiltrations in tissues and organs in the mice, which is not observed in mice with mono-transgenic TRAF3 or BCL2." (PMID 30687320, 2018).
cardiomyopathies (2 papers, 2021 to 2024). "Other proteins involved in apoptosis, such as TRAF3, which mediates pathological hypertrophy and apoptosis, was upregulated in the three cardiomyopathies." (PMID 34867990, 2021). "However, the role of TRAF3 in doxorubicin-induced cardiomyopathy remains elusive and merits exploration." (PMID 39406701, 2024). "Increased TRAF3 bound to TAK1 and promoted TAK1 autophosphorylation and activation, resulting in activated downstream MAPKs pathway and cardiomyocyte apoptosis in doxorubicin-induced cardiomyopathy (Schematic diagram)." (PMID 39406701, 2024). "The mechanism of ADAM17 enhancing TRAF3 expression in doxorubicin-induced cardiomyopathy has not been clarified." (PMID 39406701, 2024).
cervical intraepithelial neoplasia (2 papers, 2019 to 2025). "An association study has also indicated that high promoter methylation of TRAF3 correlates with the progression of cervical intraepithelial neoplasia." (PMID 39932808, 2025). "The promoter methylation levels in cGAS, MAVS, and TRAF3 genes are higher in CPL than in control, indicating that hypermethylation might be an early event in the progression of cervical intraepithelial neoplasia (CIN)." (PMID 31803230, 2019).
cholangiocarcinoma (2 papers, 2022 to 2024). A carcinoma that arises from the intrahepatic biliary tree (intrahepatic cholangiocarcinoma) or from the junction, or adjacent to the junction, of the right and left hepatic ducts (hilar cholangiocarcinoma). "In cholangiocarcinoma and gallbladder cancer, MEG3 stimulated NF-κB signaling pathway and triggered apoptosis by sponging miR-361-5p expression and activating TNF receptor-associated factor 3 (TRAF3)." (PMID 36551518, 2022).
E. coli infection (2 papers, 2023 to 2024). "Different from E. coli infection, S. aureus infection induced IRF7 and phosphorylation of IRF7 through activating TRAF3‐IKKε/TBK1 axis, bypassing MyD88." (PMID 39166412, 2024). "In this study on E.coli induction of GMECs, TLR4, TRAF3 and TRAF6 are significantly overexpressed as compared to the non-induced cells and the PPI network also suggests the key role of TLR4 and TRAF6/3 in the E. coli infection." (PMID 36604713, 2023).
Epstein-Barr virus infection (2 papers, 2017 to 2022). An infection that is caused by Epstein-Barr virus. "Beyond that, inactivation of TRAF3 function may mediate NPC tumor cells survival upon Epstein-Barr virus infection by suppressing the production of interferon immune responses." (PMID 28256603, 2017). "Finally, four significant KEGG enrichment pathways were identified (P < 0.05): beta-Alanine metabolism (SMOX, HIBCH), Pathways in cancer (GLI2, AR, TXNRD3, TRAF3, FGF16), Non-homologous end-joining (MRE11), Epstein-Barr virus infection (TRAF3, PSMD13, SIN3A)." (PMID 36330154, 2022). "Finally, the results of KEGG enrichment analysis showed four significantly enriched pathways (P < 0.05): beta-Alanine metabolism (SMOX, HIBCH), Pathways in cancer (GLI2, AR, TXNRD3, TRAF3, FGF16), Non-homologous end-joining (MRE11), Epstein-Barr virus infection (TRAF3, PSMD13, SIN3A)." (PMID 36330154, 2022).
gallstones (2 papers, 2019 to 2022). Solid crystalline precipitates in the biliary tract, usually formed in the gallbladder, resulting in the condition of cholelithiasis. "We also observed that the association of ABCG8 and TRAF3 variants with GBC was significant only when GBC samples were compared to gallstone-free individuals, indicating that the risk contribution to GBC was explained by the presence of gallstones." (PMID 30692554, 2019).
ischemic stroke (2 papers, 2019 to 2021). A stroke disorder caused by obstruction of blood flow to the brain, due to thrombotic (local blood clot formation) or embolic (due to a blood clot or other material traveling from another site) event. "In ischemic stroke, TRAF3 overexpression resulted in JNK phosphorylation, leading to neuronal apoptosis." (PMID 33414375, 2021). "In contrast, TRAF3 can stimulate TAK1 phosphorylation in ischemic stroke and hepatic ischemic injury." (PMID 33414375, 2021).
malaria (2 papers, 2017 to 2024). Malaria is a serious and sometimes fatal disease caused by a parasite that commonly infects a certain type of mosquito which feeds on humans. "Screening compound libraries for small molecules to block FOSL1 expression in cytoplasm or its interaction with TRAF3/TRIF/TBK1 may lead to therapies that can improve IFN-I response in malaria and other diseases." (PMID 28049150, 2017). "In this report, we show that, after stimulation with poly(I:C) or malaria parasite-infected red blood cells (iRBCs), FOSL1 was “translocated” from the nucleus to the cytoplasm, where it interacted with TRAF3 and TRIF to reduce IRF3 phosphorylation and IFN-I signaling." (PMID 28049150, 2017).
nasopharyngeal carcinoma (2 papers, 2018 to 2022). A carcinoma arising from the nasopharyngeal epithelium. "Furthermore, somatic mutations of TRAF3 are also frequently detected in human nasopharyngeal cancer (NPC, 8.6%)." (PMID 30294322, 2018). "Exceptions with more frequent TRAF3 and CYLD mutations include two virally-associated cancers, HPV+ HNSCC and Epstein-Barr virus-associated nasopharyngeal carcinoma (NPC)." (PMID 35634245, 2022).
prostate carcinoma (2 papers, 2016 to 2020). A carcinoma that arises from epithelial cells of the prostate gland.
subarachnoid hemorrhage (2 papers, 2021). A serious neurological disorder characterized by intracranial hemorrhage into the subarachnoid space. "Likewise, in the brain, TRAF3 promotes neuronal cell death partly through TAK1-MKK-JNK activation in both ischemia/reperfusion and subarachnoid hemorrhage injury models." (PMID 34440839, 2021).
triple-negative breast carcinoma (2 papers, 2019 to 2023). An invasive breast carcinoma which is negative for expression of estrogen receptor (ER), progesterone receptor (PR), and human epidermal growth factor receptor 2 (HER2). "A previous study reported an important β-cell-macrophage pathway mediated by miRNA-29-TRAF3, while another study found that miR-29b-3p affects the triple-negative breast cancer cell line MDA-MB-231 by targeting TRAF3 and activating the NF-κB signaling pathway." (PMID 37428806, 2023).
acute myeloid leukemia (1 paper, 2024). Acute myeloid leukemia (AML) is a group of neoplasms arising from precursor cells committed to the myeloid cell-line differentiation. "TRAF3, on the other hand, was deemed a low-risk gene in LGG and PAAD (HR < 1, P < 0.05), while it was classified as a high-risk gene in ACC, Acute Myeloid Leukemia (LAML), LIHC, THYM, and UVM (HR > 1, P < 0.05)." (PMID 38825674, 2024).
Anosmia (1 paper, 2022). An inability to perceive odors. "in TLR8 gene (presence of anosmia = 71.4% vs. absence = 33.3%) and the p.Met129Thr in TRAF3 gene (presence of anosmia = 48.1% vs. absence = 23.7%)." (PMID 36228008, 2022). "Global analysis showed some variants associated with anosmia in IFHI1, TLR8, MAVS and TRAF3: this suggests that not only the severity of symptomatology but also even some very specific clinical manifestations depend on host genomic profiles." (PMID 36228008, 2022).
bile duct cancer (1 paper, 2021). "Conversely, however, a study that used dPCR and bioinformatics methods to identify genic fusion of PUM1 and TRAF3, which was associated with poor survival in bile duct cancer patients, suggested that PUM1 is involved in the initial tumorigenic process." (PMID 33522650, 2021).
carotid artery thrombosis (1 paper, 2017). Blood clot formation in any part of the carotid arteries. "Consistent with the enhanced reactivity of the TRAF3 deficient platelets, deficiency of TRAF3 potentiated thrombosis in a FeCl3-induced carotid artery thrombosis model." (PMID 29215030, 2017). "Using the FeCl3-induced carotid artery thrombosis model, we investigated the role of TRAF3 in thrombus formation." (PMID 29215030, 2017). "Thus, we further investigated whether TRAF3 knockout affected the in vivo thrombus formation using the FeCl3-injured carotid artery thrombosis model." (PMID 29215030, 2017).
Cerebral ischemia (1 paper, 2023). Restriction of arterial blood supply to the brain associated with insufficient oxygenation to support the metabolic requirements of the tissue. "CircHECTD1 knockdown reduced the TRAF3 expression by targeting miR-133b, thereby lightening neuronal damage caused by cerebral ischemia." (PMID 37968257, 2023).
depression (1 paper, 2023). "While its direct involvement in the development of depression or BC is not known, this SNP interacts with several genes that have already been reported (i.e., TRAF3 and RCOR1), or that could play a role in the pathogenesis of the two traits (i.e., AMN, ANKRD9, and MIR4309)." (PMID 37143087, 2023).
experimental autoimmune encephalomyelitis (1 paper, 2019). An autoimmune demyelinating disease of the central nervous system that is produced experimentally in animals by the injection of homogenized brain or spinal cord in Freund's adjuvant. "Peli1 expressed in microglia can promote the degradation of TNF receptor-associated factor 3 (Traf3) by regulating TLR/MyD88 signaling and can activate microglia during the induction of experimental autoimmune encephalomyelitis (EAE)." (PMID 30967139, 2019).
fatty acid metabolic disorder (1 paper, 2016). "Considering the necessity of ubiquitination for the TAK1 autophosphorylation/activation and the K63-polyubiquitination catalysis ability of TRAF3 (refs 35, 36, 37), we examined whether an involvement of TAK1 ubiquitination exists in the TRAF3-regulated development of fatty acid metabolic disorder." (PMID 26882989, 2016).
fungal infections (1 paper, 2023). "OTUD1 regulated the production of antiviral cytokines and inflammatory cytokines by MAVS/TRAF3/TRAF6 signaling or NF-κB signaling cascades during viral and fungal infections." (PMID 38012669, 2023).
Giardia infection (1 paper, 2022). "Interestingly, Giardia infection up-regulates several downstream RIG-I signaling pathway genes during the infection, such as TRAF3, IKK, and TBK1." (PMID 35573800, 2022).
Hepatic fibrosis (1 paper, 2023). The presence of excessive fibrous connective tissue in the liver. "It was reported that miR-494-3p inhibits HSCs activation and hepatic fibrosis via targeting TRAF3 which resulted in the impaired proliferation and enhanced apoptosis." (PMID 36001230, 2023).
Hepatitis C (1 paper, 2023). "In addition, the six upregulated DETGs are involved in Hepatitis C, including CDKN1A, TRAF3, CXCL10, CASP3, EIF2S1, and IFIT1." (PMID 37107704, 2023).
HIV-1 infection (1 paper, 2025). The type species of lentivirus and the etiologic agent of acquired immunodeficiency syndrome (AIDS). "No changes were found in the mRNA expression levels of MAVS or TRAF3 genes after HIV-1 infection for 3 or 7 dpi when compared with uninfected control cultures." (PMID 41041557, 2025). "Consistent with TRAF3 upregulation, we found an increase in phosphorylated IRF3 and IRF7 at 7-days post HIV-1 infection, as compared to uninfected control cultures and with 3 dpi-infected cultures, although no significant changes were observed at the transcriptional levels for both IRF3 and IRF7." (PMID 41041557, 2025).
inflammatory bowel disease (1 paper, 2018). A spectrum of small and large bowel inflammatory diseases of unknown etiology. "A potential role for TRAF2 and TRAF3 in regulating human inflammatory bowel disease (IBD) is indicated by the finding that the expression level of these TRAF members is upregulated in the colonic tissue of IBD patients." (PMID 30140268, 2018).
lupus nephritis (1 paper, 2023). Glomerulonephritis in the context of systemic lupus erythematosus. "A recent study has revealed that TRAF3 knockdown attenuates lupus nephritis symptoms in mice, including urinary protein excretion and renal inflammation, implying that targeting TRAF3 presents a promising avenue for therapeutic intervention in SLE." (PMID 37680644, 2023).
lymph node metastasis (1 paper, 2020). "Indeed, low expression of TRAF3 in patients was related to lymph node metastasis." (PMID 33198776, 2020).
Lymphadenopathy (1 paper, 2018). Enlargement (swelling) of a lymph node. "In contrast, mouse littermates representing all the other genotypes (TRAF3-/BCL2-; TRAF3+/BCL2-, and TRAF3-/BCL2+) did not develop significant lymphadenopathy or clonal B cell expansions within the observation period of 20 months." (PMID 30687320, 2018).
lymphoid neoplasm (1 paper, 2018). A neoplasm composed of a lymphocytic cell population which is usually malignant (clonal) by molecular genetic and/or immunophenotypic analysis. "Sequencing of the VHDJH region of the heavy chain (IgH) gene locus (deduced from the transcriptome) showed that both the large B-cell and the plasma cell types of lymphoid expansions were either monoclonal or oligoclonal, thus indicating that the TRAF3/BCL2 double-tg mice develop lymphoid neoplasms." (PMID 30687320, 2018).
MALT lymphoma (1 paper, 2022). An indolent, extranodal type of non-Hodgkin lymphoma composed of small B-lymphocytes (centrocyte-like cells). "In H. pylori-positive gastric MALT lymphomas unresponsive to eradication therapy, NF-κB pathway mutations, including TNF-receptor-associated factor 3 (TRAF3) mutations and TNF-alpha-induced protein 3 (TNFAIP3) mutations, and MALT1 translocations are enriched." (PMID 35053607, 2022).
Moyamoya disease (1 paper, 2025). Moyamoya disease (MMD) is a rare intracranial arteriopathy involving progressive stenosis of the cerebral vasculature located at the base of the brain causing transient ischemic attacks or strokes. "Our findings elucidate the potential functions of the RNF213–mediated BBB integrity by targeting TRAF3 for the regulation of IFN-I signaling in moyamoya disease development." (PMID 40623121, 2025).
myasthenia gravis (1 paper, 2021). Myasthenia gravis (MG) is a rare, clinically heterogeneous, autoimmune disorder of the neuromuscular junction characterized by fatigable weakness of voluntary muscles. "We identified several genes that were specifically linked to early onset myasthenia gravis including TNIP1, ORMDL3, GSDMB, and TRAF3." (PMID 34279044, 2021).
myeloid leukemia (1 paper, 2013). A clonal proliferation of myeloid cells and their precursors in the bone marrow, peripheral blood, and spleen. "In sharp contrast, PEP005 stimulated the proliferation of primary TRAF3-/- B lymphoma cells at the dose range (10 to 100 nM) that has been previously shown to display anti-tumor activity on myeloid leukemia cells." (PMID 24131623, 2013). "In the present study, we found that AD 198 induced caspase 3 activation, PKCδ cleavage, and DNA fragmentation in TRAF3-/- tumor B cells as previously observed in myeloid leukemia cells." (PMID 24131623, 2013).
non-small cell carcinoma (1 paper, 2023). "However, the role of TRAF3 in non-small cell carcinoma remains unclear." (PMID 37798663, 2023).
oropharyngeal squamous cell carcinoma (1 paper, 2022). "We previously reported that TRAF3 and CYLD alterations in a subset of HPV+ oropharyngeal squamous cell carcinoma (OPSCC) tumors correlated with NF-κB activation and improved survival." (PMID 35634245, 2022).
ovarian tumor (1 paper, 2018). "As an ovarian tumor domain (OUT)-containing enzyme, de-ubiquitinating enzyme (DUB) A interacts directly with TRAF3 and catalyzes the cleavage of Lys-63-linked ubiquitin chains of TRAF3, thereby contributing to the dissociation of TBK1 from TRAF3 and blocking signal transductions mediated by RLRs." (PMID 30150977, 2018).
pancreatic adenocarcinoma (1 paper, 2019). "This conjugate could elevate the members of TNF and TNFR superfamilies (e.g., TNF receptor-associated factor 3 (TRAF3) and TNF receptor superfamily (TNFRSF)10B, 20, 25), the FASL/FAS pathway and different caspases (e.g., CASP5, 8 and 10) in PANC-1 pancreatic adenocarcinoma cells." (PMID 31500399, 2019).
pancreatic cancer (1 paper, 2024). "The findings from this assessment indicated that TRAF2, TRAF3, TRAF5, and TRAF7 are effective in predicting the outcomes of pancreatic cancer." (PMID 38825674, 2024).
perineurioma (1 paper, 2018). A usually benign perineurioma not associated with a nerve, arising from the soft tissues. "In particular, loss-of-function genetic alterations of TRAF2 and TRAF3 are frequently detected in B cell malignancies, and the rates of missense mutations of TRAF7 are overwhelmingly high in adenomatoid tumors, secretory meningiomas and perineuriomas." (PMID 30294322, 2018).
periodontitis (1 paper, 2022). An acute or chronic inflammatory process that affects the tissues that surround and support the teeth. "Future studies examining the expression of SGK1, TRAF3, and c-Jun and their relevance to the predisposition to periodontitis will unravel the potential therapeutic significance of these protein kinases." (PMID 35588785, 2022).